DSG3 (desmoglein 3)
Diseases named in the same sentence as DSG3 in open-access papers (continued):
Sharing a sentence is not in itself a finding about the gene and the disease.
autoimmune bullous skin disease (5 papers, 2004 to 2022). An autoimmune disease characterized by blisters on the skin. "Enzyme-linked immunoassays indices for Dsg3 and bullous pemphigoid antigen 180 decreased (Dsg3, 32; bullous pemphigoid antigen 180, 70.44)." (PMID 33466152, 2021). "Today the pathogenicity of anti-Dsg3 autoantibodies is a datum of fact since transfer of patient derived anti-Dsg3 serum IgG antibodies into mice induces a bullous skin disease resembling PV." (PMID 17062151, 2006). "PV is an autoimmune bullous skin disease characterized by autoantibodies to a desmosomal adhesion molecule, the cadherin desmoglein-3 (Dsg3)." (PMID 15588331, 2004).
dermatitis (5 papers, 2013 to 2025). An inflammatory process affecting the skin. "These Dsg3H1 T cells can cause skin inflammation, by exhibiting cytotoxic activity against Dsg3-expressing keratinocytes and promoting anti-Dsg3 antibody production, which results in blister formation." (PMID 37308897, 2023). "Although less likely, they hypothesized that Desmoglein 3-specific CD4+ T cells induce interphase dermatitis based on data from a mice study." (PMID 40686696, 2025). "Despite the absence of obvious clinical or histopathological dermatitis in the aged mice, these results suggest that peripheral tolerance against Dsg3-specific T cells is at least partially disrupted in aged mice." (PMID 37308897, 2023).
myasthenia gravis (5 papers, 2023 to 2025). Myasthenia gravis (MG) is a rare, clinically heterogeneous, autoimmune disorder of the neuromuscular junction characterized by fatigable weakness of voluntary muscles. "Currently, two clinical trials are evaluating CAAR-T cell therapy targeting muscle-specific tyrosine kinase (MuSK) in myasthenia gravis and desmoglein-3 (Dsg-3) in mucosal-dominant pemphigus vulgaris." (PMID 39931050, 2025). "Preclinical studies on MuSK-CAART for myasthenia gravis treatment and desmoglein 3 (DSG3)-CAART for mucosal pemphigus vulgaris have shown that both CAARTs retained efficient levels of cytolysis activity in the presence of soluble antibodies." (PMID 38673811, 2024).
oral cancer (5 papers, 2021 to 2023). "This study aimed to uncover molecular mechanisms through comparative transcriptome analysis in oral cancer cells, defining potential key genes and associated biological processes related to DSG3 expression." (PMID 38067138, 2023). "This current study aimed to expand our previous report to uncover differentially expressed genes (DEGs) between DSG3-overexpressing and vector control-expressing oral SCC cells (H413) in order to broaden our understanding of DSG3 in oral cancer cells." (PMID 38067138, 2023). "In the context of oral cancer, DSG3 is likely involved in modifying the tumour microenvironment by promoting collagen deposition, thereby facilitating tumour progression." (PMID 38067138, 2023). "The review also discusses the potential target of YAP in oral cancer therapy and the recent finding of the unprecedented role of the desmosomal cadherin desmoglein-3 (DSG3) in regulating Hippo-YAP signaling." (PMID 37304649, 2021). "Alternatively, these results may simply reflect the more dynamic nature or dysregulation of the desmosomes in oral cancer cells with overexpression of DSG3." (PMID 38067138, 2023). "The biomarker proteins were the cell-bound protein desmoglein 3 (DSG3), a metastatic biomarker for oral cancer and VEGF-A, an oral cancer biomarker expressing outside the cancer cells (VEGF = vascular endothelial growth factor)." (PMID 34206405, 2021). "The abnormal expression of DSC3, DSG3, and β-catenin was found in oral carcinomas and that the reduced or absent expression of β-catenin had a positive correlation with reduced or absent expression of DSC3 in 24 patients with lymph node metastasis." (PMID 36982827, 2023). "Hence, our studies provide a unique working model for DSG3 in regulating the Hippo‐YAP pathway and submit mutually exclusive regulation between DSG3 and YAP in oral cancer cells." (PMID 35000271, 2022).
lung squamous cell carcinoma (4 papers, 2017 to 2020). "Actually, it has been reported that DSG3 can be the useful biomarker for squamous cell lung cancer." (PMID 28821283, 2017). "However, other researchers revealed that DSG3 was overexpressed in squamous cell lung cancer." (PMID 32869947, 2020).
lymph node metastasis (4 papers, 2013 to 2023). "DSG3 has been identified as a biomarker for precise detection of HNC lymph node metastasis and can clearly distinguish clinically positive and negative lymph nodes." (PMID 34203070, 2021). "These advances suggest that DSG3 can help clinicians identify false-negative lymph node metastasis to improve diagnostic accuracy and provide treatment strategies for patients with HNC." (PMID 34203070, 2021). "Furthermore, several reports have already shown that DSG3 is a useful marker for detecting lymph node metastasis in these patients." (PMID 26700817, 2016).
oral squamous cell carcinoma (4 papers, 2020 to 2025). "Furthermore, the role of Dsg3 in oral squamous cell carcinoma, by promoting enzymes that degrade the extracellular matrix and enhance tumor invasiveness, highlights the complex functions of desmogleins beyond autoimmunity." (PMID 40558105, 2025).
COVID-19 (3 papers, 2022 to 2023). A disease caused by infection with severe acute respiratory syndrome coronavirus 2. "In this study, we have measured desmosomal protein levels and investigated the presence of anti-DSG1, DSG2, and DSG3 antibodies in sera from patients with acute COVID-19 and in those who have recovered from COVID-19 infection." (PMID 37095599, 2023). "We tested the 30 samples from the COVID-19 groups that were positive for skin autoantibodies (intercellular cement staining) by immunofluorescence and found none of these samples were positive for anti-DSG1 or anti-DSG3 autoantibodies." (PMID 37095599, 2023).
head and neck squamous cell carcinoma (3 papers, 2014 to 2023). A squamous cell carcinoma that arises from any of the following anatomic sites: lip and oral cavity, nasal cavity, paranasal sinuses, pharynx, larynx, and salivary glands. "DSG3 has been reported to be expressed at high levels in head and neck squamous cell carcinoma, and has been implicated as a potential biomarker for detection of this cancer's lymph node metastases." (PMID 24140581, 2014). "Recent evidences suggest that DSG3 might play an important role in the prognostic assessment of head and neck squamous cell carcinoma, skin cutaneous melanoma, and triple negative breast cancer." (PMID 36906533, 2023). "Instead, only antibodies with non-pathogenic anti-Dsg3 variable regions should be used as a tool for targeting drug delivery, for example to Dsg3+ head and neck squamous cell carcinomas or inflammatory skin conditions." (PMID 27304671, 2016).
oral lichen planus (3 papers, 2018 to 2025). Oral lichen planus is a chronic inflammatory oral condition of unknown aetiology characterized by T-cell-mediated chronic immune response and abnormal epithelial keratinization cycle. "Desmoglein 3 autoantibodies were detected in higher concentrations in oral lichen planus tissues compared to healthy controls." (PMID 40481453, 2025). "Increased concentration of desmoglein 3 autoantibodies is correlated with an increase in oral lichen planus clinical severity scores and vice versa." (PMID 40481453, 2025). "Interestingly, within the literature there are cases of oral lichen planus with circulating anti-Dsg3 antibodies, which are typically characteristic of PV." (PMID 29340948, 2018).
psoriasis (3 papers, 2018 to 2025). An autoimmune condition characterized by red, well-delineated plaques with silvery scales that are usually on the extensor surfaces and scalp. "More recently, a psoriasis mice model was developed based on an autoimmune mechanism, wherein injection of IL-17-producing CD4+ T cells recognizing desmoglein 3 as autoantigen was able to develop psoriasis-like lesions." (PMID 29316717, 2018). "In the psoriasis lesional skin, high expression of desmocollin 2 (DSC2) and desmoglein 3 (DSG3) was also observed, in contrast to the low expression of desmocollin 1 (DSC1) and desmoglein 1 (DSG1)." (PMID 36841845, 2023).
alopecia (2 papers, 2019 to 2023). Hair loss usually from the scalp. "DSC3/DSG3 mice show more lesions and alopecia on the face and in the periocular area, erosions on the forelegs, with exacerbated erythema, while in DSC3 mice intense erythema and patchy hair loss are the main phenotypic aspects." (PMID 31275323, 2019). "Lastly, Rag2−/− mice actively producing anti-DSG3 antibodies displayed alopecia." (PMID 31275323, 2019). "Alopecia, erosions, and blistering were observed in the skin of DSG1, DSG3 and DSG1/DSG3 models, while lesions in the mucosa were observed only in DSG3 and DSG1/DSG3 animals." (PMID 37237515, 2023).
breast carcinoma (2 papers, 2018 to 2021). "Similarly, overexpression of the Desmoglein 3 (DSG3) oncogene has been correlated with DSG3 gene amplification in breast cancer tissues." (PMID 35011637, 2021).
Erythema (2 papers, 2019 to 2024). Redness of the skin, caused by hyperemia of the capillaries in the lower layers of the skin. "Unlike the DSG3 and DSC3/DSG3 models, the main features of DSC3 mice consisted of an intense erythema." (PMID 31275323, 2019). "Furthermore, we found that, despite the presence of anti‐Dsg3 antibodies, CFA failed to facilitate the breach of tolerance against self‐Dsg3, as evidenced by the lack of significant gross phenotype changes manifested by paw swelling and slight erythema and histological examination findings." (PMID 39031979, 2024).
esophageal cancer (2 papers, 2020 to 2021). A primary or metastatic malignant neoplasm involving the esophagus. "In addition, the decreased expression of DSG3, SPRR3 and MAL, which were all also decreased under conditions of ATRA absence in our experiment, were reported to be related to a poor prognosis of esophageal cancer." (PMID 32556644, 2020).
esophageal SCC (2 papers, 2022 to 2025). "In esophageal SCC, DSG3 was positive in 100% of cases and proved especially useful in well-differentiated tumors with weak or absent p40 expression." (PMID 40427131, 2025). "In this study, significant DSG3 immunoreactivities were observed in all three differentiation components in esophageal SCC." (PMID 35251162, 2022). "If the immunoreactivity cutoff was to be raised to 10%, DSG3 positivity would have been 0% for esophageal adenocarcinoma, but still 100% for esophageal SCC." (PMID 35251162, 2022). "The findings of this study provide evidence regarding the optimized choice of squamous differentiation markers in routine pathology practice as well as detailed characterization of DSG3 expression in esophageal SCC." (PMID 35251162, 2022). "Although CK5/6 IHC showed similar immunoreactivities in esophageal SCC, DSG3 IHC was easier to interpret due to its distinct membranous staining patterns." (PMID 35251162, 2022). "Now, for the first time, our studies provided detailed characterization of DSG3 expression in esophageal SCC, which paved the way for future research on the therapeutic applications of anti-DSG3 antibody in esophageal SCC patients." (PMID 35251162, 2022). "We characterized desmoglein 3 (DSG3) immunohistochemistry in esophageal SCC, esophageal adenocarcinoma, small-cell lung carcinoma, and large B-cell lymphoma, alongside P40 and CK5/6." (PMID 35251162, 2022). "Therefore, our findings indicated that DSG3 is a highly specific marker to differentiate esophageal SCC from adenocarcinoma." (PMID 35251162, 2022). "Interestingly, we did have one esophageal SCC case with a minor small-cell carcinoma component, and this minor small-cell carcinoma component showed 0% DSG3 immunoreactivity." (PMID 35251162, 2022). "This is the first study to show DSG3 as a sensitive and specific marker for esophageal SCC." (PMID 35251162, 2022). "In pathology practices, the most important differentiation diagnosis for esophageal SCC is esophageal adenocarcinoma; therefore, 18% of DSG3 positivity appeared to be not ideal at first look." (PMID 35251162, 2022). "However, none of the adenocarcinoma cases had more than 10% DSG3 immunoreactivity, and they all showed weak cytoplasmic staining patterns rather than the distinct membranous patterns seen in esophageal SCC." (PMID 35251162, 2022). "Notably, none of the adenocarcinoma cases showed more than 10% DSG3 immunoreactivity which was weak cytoplasmic staining rather than the distinct membranous staining seen in esophageal SCC." (PMID 35251162, 2022). "However, the immunohistochemical analysis of DSG3 in esophageal SCC has not been reported yet." (PMID 35251162, 2022).
gastric cancer (2 papers, 2015 to 2025). A primary or metastatic malignant neoplasm involving the stomach. "Among the genes exhibiting the most significant upregulated expression in the FB-E6/E7-HPV80 model, DSG3 is expressed in head and neck SCC but also in breast, colorectal, and gastric cancer, implicated in the cell proliferation, metastasis, and modulation of the tumor microenvironment." (PMID 40508156, 2025).
IgA pemphigus (2 papers, 2021 to 2024). Immunoglobulin A (IgA) pemphigus is a group of newly characterized immune-mediated intraepidermal blistering skin diseases. "Oral lesions in IgA pemphigus may be clinical clue of having anti-Dsg3 IgA that cannot be routinely examined." (PMID 38577061, 2024).
skin cancer (2 papers, 2012 to 2021). "To better understand the failure of Dsg3 loss to enhance UVB-induced skin cancer development, we therefore examined whether Dsg3 deficiency impaired the apoptotic response in the epidermis after UVB treatment." (PMID 23185521, 2012). "Here, we analyze the consequence of Dsg3 nullizygosity for skin cancer development using two different tumor models." (PMID 23185521, 2012). "Thus, Dsg3 does not display a clear function as a tumor suppressor in these mouse skin cancer models." (PMID 23185521, 2012).
-only disease (1 paper, 2020). "Clinical variants include mucosal-only disease (which correlates with circulating anti-Dsg3 autoantibodies), cutaneous-only disease (anti-Dsg1 antibody predominant), or more frequently, mucocutaneous involvement (presence of both anti-Dsg1 and anti-Dsg3 antibodies)." (PMID 32642305, 2020).
allergic rhinitis (1 paper, 2023). Inflammation of the nasal mucous membranes caused by an IgE-mediated response to external allergens. "This study assessed the mRNA expression levels of various tight junctions, including occludin (OCLN), claudin-3 and −7 (CLDN3 and CLDN7), desmoglein 3 (DSG3), and thymic stromal lymphopoietin (TSLP) in 30 individuals with Allergic Rhinitis (AR) and 30 non-allergic controls." (PMID 37692890, 2023).
aphthous ulceration (1 paper, 2022). "Using ELISA, the authors found out in this retrospective study that the level of both anti-Dsg1 and anti-Dsg3 IgG antibodies was significantly higher in patients with erosive OLP compared to healthy control (HC), patients with recurrent aphthous ulceration, and patients with non-erosive OLP." (PMID 36263026, 2022).
basal cell carcinoma (1 paper, 2021). A carcinoma involving the basal cells. "In addition, aberrant expression of Dsg3 is also reported in basal cell carcinoma (BCC) where its expression correlates with Dsg2 at the mRNA level but differ greatly at the protein level, with the loss of coordination of DSG2 and DSG3 expression and a reduction of DSG3 in BCC." (PMID 34206820, 2021).
bronchiolitis obliterans (1 paper, 2019). "In addition to mucocutaneous lesions, marked infiltration of CD8+ T cells is observed in PNP-associated bronchiolitis obliterans and in the lungs of DSG3−/− mice injected with IgGs from PNP sera." (PMID 31214197, 2019). "Thus, anti-Dsg3 antibody might contribute to the pathogenesis of bronchiolitis obliterans." (PMID 31214197, 2019).
cataract (1 paper, 2025). Partial or complete opacity of the crystalline lens of one or both eyes that decreases visual acuity and eventually results in blindness. "The presence of Cataracts may indicate persistent anti-Dsg1 positivity after CR, while elevated anti-Dsg3 titers and PDAI scores at baseline may predict sustained elevated anti-Dsg3 post-CR." (PMID 40433384, 2025).
cholera (1 paper, 2019). "Although Dsg1 is 65% homologous to Dsg3, only two mAbs had binding activity toward Dsg1, while no mAbs cross reacted with influenza or cholera proteins." (PMID 31340153, 2019).
chronic rhinosinusitis (1 paper, 2023). Chronic form of sinusitis. "Silencing DSG3 was reported to inhibit the activation of the Wnt/β-catenin signaling pathway in mice with chronic rhinosinusitis." (PMID 36982827, 2023).
eczema (1 paper, 2025). "Anti-Dsg3 and anti-BP230 antibody levels were significantly higher in eczema patients, while anti-Dsg3 antibody levels were also significantly higher in herpes zoster patients than in the healthy population." (PMID 40661962, 2025).
esophageal adenocarcinoma (1 paper, 2022). A malignant tumor with glandular differentiation arising predominantly from Barrett mucosa in the lower third of the esophagus. "Using a 5% immunoreactivity cutoff, the DSG3 positivity was 18% for esophageal adenocarcinoma, 0% for small-cell lung carcinoma, and 0% for large B-cell lymphoma." (PMID 35251162, 2022). "No esophageal adenocarcinoma cases showed more than 10% DSG3 immunoreactivity with only weak cytoplasmic staining." (PMID 35251162, 2022).
influenza (1 paper, 2019). An acute viral infection of the respiratory tract, occurring in isolated cases, in epidemics, or in pandemics; it is caused by serologically different strains of viruses (influenzaviruses) designated A, B, and C, has a 3-day incubation period, and usually lasts for 3 to 10 days. "Interestingly, Dsg3-specific MBCs expressed the activation marker CD71, which was recently shown to be transiently expressed on newly generated MBCs in healthy influenza vaccinees." (PMID 31340153, 2019).
leishmaniasis (1 paper, 2022). Infectious disease that is transmitted through the bite of hematophagous female phlebotomine sand flies. "Additionally, they showed that sera from Tunisian leishmaniasis patients exhibited high titers of anti-PpSP32 (n=56), anti-Dsg1 (n=14), and anti-Dsg3 (n=17) antibodies, which positively correlated." (PMID 35693761, 2022).
morphea (1 paper, 2022). "Furthermore, confirmatory ELISA for the presence of DSG3 antibodies in the sera of morphea patients was negative (data not shown)." (PMID 35073943, 2022).
nicotine dependence (1 paper, 2012). Physical and psychological dependence on nicotine. "However, one gene, DSG3,is genome-wide significantly (P = 2.70E − 6) associated with nicotine dependence in the white men, according to the gene-based method." (PMID 23365539, 2012). "This method identified one genome-wide significant gene, DSG3 (P value = 1.99E − 6) for nicotine dependence in white men." (PMID 23365539, 2012).
Pruritus (1 paper, 2025). Pruritus is an itch or a sensation that makes a person want to scratch. "Patients with mucosal lesion and Nikolsky sign had higher levels of anti-Dsg1 and anti-Dsg3 antibodies, and patients with pruritus had higher levels of anti-BP180 and anti-BP230 antibodies." (PMID 40661962, 2025). "Elevated anti-Dsg3 associated with mucosal lesions, anti-Dsg1/anti-Dsg3 associated with Nikolsky sign, while anti-BP180/anti-BP230 levels were linked to pruritus." (PMID 40661962, 2025). "Autoantibody levels correlated with disease severity and clinical symptoms, with elevated levels of anti-Dsg3 associated with mucosal lesions, anti-Dsg1/anti-Dsg3 associated with Nikolsky sign, and elevated anti-BP180/anti-BP230 levels linked to pruritus." (PMID 40661962, 2025). "Autoantibody levels correlated with disease severity and specific clinical symptoms, with elevated anti-Dsg3 associated with mucosal lesions, elevated anti-Dsg1/anti-Dsg3 associated with Nikolsky sign, and elevated anti-BP180/anti-BP230 levels linked to pruritus." (PMID 40661962, 2025).